TERT (telomerase reverse transcriptase)
Diseases named in the same sentence as TERT in open-access papers (continued):
Sharing a sentence is not in itself a finding about the gene and the disease.
Cirrhosis (30 papers, 2012 to 2025). A chronic disorder of the liver in which liver tissue becomes scarred and is partially replaced by regenerative nodules and fibrotic tissue resulting in loss of liver function. "Loss‐of‐function germline mutations in TERT predispose to a spectrum of familial liver diseases characterised by steatosis and possible evolution to cirrhosis and HCC." (PMID 39945383, 2025). "The mutation of the TERT promoter in cirrhosis leads to the transformation of precancerous lesions into cancerous lesions." (PMID 37046429, 2023). "In a study examining hepatic nodules development in cirrhosis, the hotspot TERT promoter mutations were detected in 6% of the low-grade dysplastic nodules, 19% of the high-grade dysplastic nodules, 61% of early HCC, and 41% of established HCC." (PMID 33946181, 2021). "TERT promoter mutations have been reproducibly associated with cirrhosis and cirrhosis-associated HCC." (PMID 33457451, 2020). "TERT promoter mutations were found in 6% of low grade dysplastic nodules and 19% of high-grade dysplastic nodules in cirrhosis, and were dramatically increased in early HCCs (61%) without additional recurrent HCC driver gene mutations." (PMID 33457451, 2020). "A previous study reported on one case of HCC in a patient with cirrhosis associated with non-alcoholic fatty liver carrying a TERT mutation." (PMID 28813500, 2017). "In conclusion, our observations indicate that TERT variants are observed in a small number of patients with HCC associated with cirrhosis." (PMID 28813500, 2017). "Our previous analysis of the prevalence of telomerase mutations in patients with cirrhosis of diverse etiologic backgrounds—mainly alcohol-, hepatitis B- or C-induced—revealed an enrichment for TERT gene mutations compared to healthy controls." (PMID 28813500, 2017). "In particular, it has been reported that TERT promoter mutations are the earliest genetic events in the multistep process of hepatocarcinogenesis related to cirrhosis." (PMID 27661004, 2016). "TERT promoter mutations are the earliest genetic events in the multistep process of hepatocarcinogenesis related to cirrhosis." (PMID 27661004, 2016). "TERT promoter mutations have been also identified as a frequent genetic alteration in dysplastic hepatocellular nodules arising in cirrhosis and as a key event in malignant transformation of hepatocellular adenoma." (PMID 27276713, 2016). "More recently, constitutional “loss-of-function” type of telomerase (TERT or TERC genes) mutations have been identified as a risk factor for cirrhosis." (PMID 23691139, 2013). "Alternatively, the TERT promoter region mutations may arise at some point between cirrhosis and the ‘initiated cell’ or ‘preneoplastic lesion’ stages." (PMID 35739588, 2022). "Clinical data and etiology of cirrhosis in four HCC patients harboring TERT mutations." (PMID 28813500, 2017). "Similarly, two studies investigated the frequency of telomerase mutations in patients with sporadic cirrhosis compared to healthy controls and demonstrated mutation missense mutations in the Telomerase Reverse Transcriptase (TERT) and TERC genes in diseased patients." (PMID 38349865, 2024). "Rare mutations in the telomerase reverse transcriptase (TERT) promoter may arise in NAFLD–cirrhosis, in 10–20% of both low-grade and high-grade dysplastic nodules and in familial HCC, suggesting that TERT germline genetic variants may be involved in tumor initiation." (PMID 33920670, 2021). "Older patients, many of whom had TERT and RTEL1 variants, were frequently affected by ILD or cirrhosis." (PMID 40179146, 2025). "According to the Calado study, there was a greater incidence of gene variants in the TERT and TERC genes among individuals with cirrhosis compared to the control group." (PMID 37720239, 2023). "Herein, we report a successful liver transplantation in a patient who suffered hepatoportal cirrhosis from telomerase reverse transcriptase (TERT)-telomeropathy." (PMID 37539400, 2023).
Cirrhosis (continued). "The study additionally reveals the existence of TERT and TERC mutations among individuals who have been clinically diagnosed with hepatic cirrhosis." (PMID 37720239, 2023). "This novel heterozygous TERT variant was identified in a 65-year-old male with advanced HCC and cirrhosis secondary to chronic hepatitis C infection and alcohol ingestion." (PMID 28813500, 2017). "The multivariate analysis confirmed that older age (P = 0.006), advanced BCLC stage (P = 0.032), and patients without cirrhosis history (P = 0.027) were independent factors associated with TERT promoter mutations." (PMID 28460432, 2017). "A novel TERT variant, A243V, was identified in a 65-year-old male with advanced HCC and cirrhosis secondary to chronic hepatitis C virus (HCV) and alcohol ingestion, but direct assay measurements in vitro did not detect modulation of telomerase enzymatic activity or processivity." (PMID 28813500, 2017). "In the present study, we found that constitutional TERT missense variants were found in 3.3% of patients diagnosed with HCC associated with cirrhosis, but peripheral blood leukocyte telomere length did not correlate with HCC development." (PMID 28813500, 2017). "In contrast, we found no TERT mutation in liver tissues from 20 control patients with cirrhosis or hepatolithiasis without HCC." (PMID 27056898, 2016). "A total of 129 viral related cirrhosis autologous tissues along with 11 liver biopsies from non-tumor patients were analyzed for TERT promoter mutations and found all negatives." (PMID 27276713, 2016). "In patient #5, a 57‐year‐old male with a history of cirrhosis associated with SLD and portal hypertension, who subsequently developed HCC, we identified a rare variant (NM_001193376: p.H412Y) in TERT gene, allowing a suggested diagnosis of autosomal dominant TERT‐associated telomerase syndrome." (PMID 39945383, 2025). "We found strong correlations between genetic effects on HCC and hepatic steatosis (r2 = 0.75), and HCC and cirrhosis (r2 = 0.69), whereas only three loci (APOE, HFE, and TERT) had concordant effects on HCC and biliary tract cancer." (PMID 40823170, 2025). "Another study observed that TERT levels were significantly associated with reduced overall survival, having analyzed concentrations of TERT DNA in patients with HCC, cirrhosis and chronic hepatitis." (PMID 31608239, 2019). "In contrast to cirrhosis, HCC is known to reactivate TERT expression, display high telomerase activity and stabilize telomeres." (PMID 23691139, 2013). "TERT expression was significantly elevated in HCC tissues compared to non-tumour liver tissue samples diagnosed histologically as cirrhosis or hepatitis (p < 0.001)." (PMID 40650279, 2025). "We measured TERT protein expression by IHC in 28 HCCs (15 with mutation and 13 without mutation) and 8 non-HCC liver tissues including live cirrhosis tissues and normal liver tissues." (PMID 27056898, 2016). "Indeed, TERT ctDNA has been reported to be more frequently found in HCC patients with cirrhosis than in those without." (PMID 35884434, 2022).
dyskeratosis congenita (30 papers, 2007 to 2025). Dyskeratosis congenita (DC) is a rare ectodermal dysplasia that often presents with the classic triad of nail dysplasia, skin pigmentary changes, and oral leukoplakia associated with a high risk of bone marrow failure (BMF) and cancer. "To explore this question, we analyzed a large kindred with multiple dyskeratosis congenita cases and a heterozygous pathogenic variant in the TERT gene (ClinicalTrials.gov Identifier: NCT00027274)." (PMID 40459934, 2025). "The patient was diagnosed as TERT de novo mutation-related dyskeratosis congenita and porto-sinusoidal vascular disease." (PMID 39849589, 2025). "Despite a few reports describing its relation with dyskeratosis congenita, TERT gene is currently only confirmed to be associated with shortened telomeres, and cannot explain all characteristics of the 5p deletion syndrome." (PMID 35911393, 2022). "Dyskeratosis congenita, a rare hereditary disorder complicated by the development of pulmonary fibrosis in 20% of patients, is associated with mutations within either TERT or TERC that lead to decreased telomerase activity." (PMID 23075428, 2012). "Haploinsufficiency for TERT leads to premature telomere shortening in human and causes the aging disease known as dyskeratosis congenita." (PMID 21347393, 2011). "On the other hand, even a partial telomerase deficiency in humans brought about by mutations in either TR or TERT has been associated with early or late onset bone marrow failure, as seen in patients with dyskeratosis congenita and aplastic anemia." (PMID 18846223, 2008). "Finally, they do not correspond with the patient’s medical and family history; for example, sequence changes of the COL7A1 or the TERT genes are associated with epidermolysis bullosa or dyskeratosis congenita, respectively." (PMID 35205015, 2022). "Similar observations were made previously for some tumor cell lines in which telomerase activity is limited by levels of TR, and might explain the tissue-specific impact of TERT and TR mutations in patients with dyskeratosis congenita." (PMID 26194807, 2015). "TA is also required for the maintenance of normal stem cells, and in patients with dyskeratosis congenita (DKC) inactivating mutations in TERT and TERC may lead to the loss of normal hematopoietic stem cells and aplastic anemia." (PMID 20824134, 2010). "Rare variations/mutations in the TERT gene have been described as a risk factor for acute myelogenous leukemia and also explain a proportion of the inherited bone marrow failure family pedigrees with dyskeratosis congenita, a cancer predisposition syndrome." (PMID 20700438, 2010). "The remaining 17 patients presented conditions such as familial myeloproliferative neoplasms, dyskeratosis congenita (DC) [TERT, DKC1 variants], and Chediak-Higashi syndrome." (PMID 40047910, 2025). "Therefore, we speculate that the TERT de novo c.2286 + 1G/A mutation can directly interfere with TERT enzymatic activity, resulting in telomere shortening, dyskeratosis congenita, and PSVD." (PMID 39849589, 2025). "The human condition dyskeratosis congenita (DC) is associated with heterozygous mutations in TERT and TERC and hemizygous mutations in the telomerase enzyme component dyskerin (DKC)." (PMID 35409012, 2022). "We reported mutations in TERC and telomerase reverse transcriptase (TERT) to be risk factors for apparently acquired aplastic anemia, a marrow failure disease occurring in patients who lack the typical physical anomalies and family history of dyskeratosis congenita." (PMID 19936245, 2009). "Dyskerin mutations are associated in autosomal dominant fashion with another hereditary BMF syndrome, dyskeratosis congenita (DC), but mutations of other members of the telomerase complex, chiefly TERT and TERC, have been implicated in predisposition to both AA and MDS." (PMID 29416752, 2018).
dyskeratosis congenita (continued). "Other conditions linked to telomere dysfunction are also associated to HSC failure and leukemia predisposition such as dyskeratosis congenita (caused by TERC mutation) and a hereditable heterozygous mutation of TERT responsible for autosomal dominant aplastic anemia." (PMID 34736527, 2021). "All of these family members had the same abnormality in the TERT gene and suffered from a rare inherited disease called dyskeratosis congenita (DC)." (PMID 40095034, 2025). "Dyskeratosis congenita (DKC) is a progressive dermatological condition characterized by premature graying and wrinkling, nail dystrophy, and abnormal pigmentation, and caused by mutations in the telomerase RNA component (TERC) and telomerase reverse transcriptase (TERT) genes." (PMID 32518230, 2020). "Haploinsufficiency for TERC or TERT leads to progressive telomere shortening and autosomal dominant dyskeratosis congenita (DC)." (PMID 17875000, 2007). "Telomeropathies include dyskeratosis congenita (DKC), in which a disease-causing variant is often found within the dyskerin (DKC1) gene on the X chromosome or other telomere maintenance genes such as TINF2, TERC, TERT, CTC1, and other genes." (PMID 40440483, 2025). "Individuals with dyskeratosis congenita (DC), a cancer susceptibility and inherited bone marrow failure syndrome (IBMFS), have mutations in genes important in telomere biology, including DKC1, TERC, TERT, TINF2, NHP2 and NOP10." (PMID 21113082, 2010). "Dyskeratosis congenita (DC) is a disorder of excessive telomere attrition due to defects in the telomerase complex, either related to the disease gene (DKC1), and/or other genes involved in telomere repair (TIN2, TERC, TERT, amongst others)." (PMID 38612901, 2024).
follicular thyroid carcinoma (29 papers, 2009 to 2025). "This study aimed to demonstrate the ultrasonographic (US) features of TERT promoter-mutated follicular thyroid cancer (FTC) and evaluate their predictive performance." (PMID 38961252, 2024). "Even so, it makes sense that highly proliferative follicular thyroid carcinomas associated with TERT gene aberrancies are indeed high-grade lesions, which is also the case in this study." (PMID 35305239, 2022). "By contrast, TERT promoter mutations are exclusively associated with malignancy, are invariably associated with invasive growth in papillary and follicular carcinomas, and their prevalence increases in poorly differentiated and anaplastic thyroid carcinomas." (PMID 33543394, 2021). "We recently observed a specific global mRNA pattern in TERT promoter mutated follicular thyroid carcinomas (FTCs) compared to FTCs with TERT promoter wild-type sequences, and the former group was enriched in mRNAs associated to various metabolic pathways." (PMID 34676499, 2021). "The undifferentiated thyroid carcinoma cell line (8505C) presented the C250T mutation in heterozygosis and the follicular thyroid carcinoma cell line (WRO) was wild-type for both TERT promoter mutations." (PMID 33776938, 2021). "Mutations of the Telomerase reverse transcriptase (TERT) gene promoter are recurrently found in follicular thyroid carcinoma (FTC) and follicular tumors of uncertain malignant potential (FT-UMP), but nearly never in follicular thyroid adenoma (FTA)." (PMID 31561592, 2019). "In our previous study, TERT promoter mutation led to telomerase activation in papillary and follicular thyroid cancer." (PMID 24758186, 2014). "We analyzed the profile of 53BP1 expression and NRAS codon 61 and TERT-promoter (TERT-p) mutations in 16 cases of TFTs showing NN with PDc compared to 30 adenomatous goiters, 31 follicular adenomas, 15 minimally invasive follicular carcinomas (FCs), and 11 widely invasive FC cases." (PMID 35892838, 2022). "The clinical meaning of TERT promoter mutation in follicular variant PTC or follicular thyroid cancer is still unknown, and a large number of cases should be accumulated." (PMID 34070093, 2021). "Thyroid follicular carcinoma often presents with the following gene mutations: RAS (50%), PPARG fusion (30%), PIK3CA (10%), PTEN (10%), and TERT promoter mutations (20%)." (PMID 38758843, 2024). "TERT promoter mutations were positive in 40/181 (22.1%) conventional PTC, 17/62 (27.4%) FVPTC, 9/34 (26.5%) TCPTC, 2/8 (25%) DSPTC, 3/7 (43%) follicular thyroid cancer (FTC) and 1⁄4 (25%) Oncocytic thyroid cancer." (PMID 37859987, 2023). "Telomerase reverse transcriptase (TERT) gene aberrancies correlate to adverse prognosis in follicular thyroid carcinoma (FTC)." (PMID 37486076, 2023). "In 2 cases of follicular thyroid carcinomas with molecular changes, 1 patient carried both HRAS and TERT mutations, and 1 patient carried TERT mutation." (PMID 36737779, 2023). "Upregulation of the telomerase reverse transcriptase (TERT) gene is a frequent finding in follicular thyroid carcinomas (FTCs) with metastatic features." (PMID 34011619, 2021). "Both the follicular thyroid carcinoma (FTC) and the metastasis were investigated for the presence of BRAF/RAS and TERT promoter mutations." (PMID 31417495, 2019). "For luciferase assay, we used TTA1 (ATC) and HTori‐3 (normal human thyroid) cell lines with WT TERT promoter sequence, and FTC‐133 (follicular thyroid cancer) cell line carrying the c.‐124C > T mutation." (PMID 31408918, 2019). "Using logistic regression analysis, the authors were able to identify two genes, TERT and TTF3, whose combination was able to distinguish adenomas and low grade follicular carcinomas from aggressive follicular carcinomas." (PMID 20514214, 2009).